H2BC1 (H2B clustered histone 1)
Description:
Variant histone specifically required to direct the transformation of dissociating nucleosomes to protamine in male germ cells (By similarity). Entirely replaces classical histone H2B prior nucleosome to protamine transition and probably acts as a nucleosome dissociating factor that creates a more dynamic chromatin, facilitating the large-scale exchange of histones (By similarity). Core component of nucleosome (By similarity). Nucleosomes wrap and compact DNA into chromatin, limiting DNA accessibility to the cellular machineries which require DNA as a template (By similarity). Histones thereby play a central role in transcription regulation, DNA repair, DNA replication and chromosomal stability (By similarity). DNA accessibility is regulated via a complex set of post-translational modifications of histones, also called histone code, and nucleosome remodeling (By similarity). Also found in fat cells, its function and the presence of post-translational modifications specific to such cells are still unclear.
Synonyms: TSH2B.1; hTSH2B; HIST1H2BA; TSH2B; bA317E16.3; STBP; H2BFU; TH2B
Tractability: Small molecule: a structure with a bound ligand is known. PROTAC: UniProt records ubiquitination sites on it; ubiquitination databases record sites on it.
Gene: Protein-coding gene on chromosome 6 (25,726,777 to 25,727,345, forward strand). Ensembl gene ENSG00000146047.
Subcellular location: Nucleus; Chromosome
Pathways (Reactome):
Gene expression (Transcription): B-WICH complex positively regulates rRNA expression; DNA methylation; ERCC6 (CSB) and EHMT2 (G9a) positively regulate rRNA expression; MLL4 and MLL3 complexes regulate expression of PPARG target genes in adipogenesis and hepatic steatosis; NoRC negatively regulates rRNA expression; PRC2 methylates histones and DNA; RNA Polymerase I Promoter Escape; RNA Polymerase I Promoter Opening; RUNX1 regulates genes involved in megakaryocyte differentiation and platelet function; RUNX1 regulates transcription of genes involved in differentiation of HSCs; Regulation of endogenous retroelements by KRAB-ZFP proteins; Regulation of endogenous retroelements by Piwi-interacting RNAs (piRNAs); Regulation of endogenous retroelements by the Human Silencing Hub (HUSH) complex; SIRT1 negatively regulates rRNA expression; Transcriptional regulation by small RNAs
Chromatin organization: CHD1 and CHD2 subfamily; CHD6, CHD7, CHD8, CHD9 subfamily; ChAHP complex assembly; HATs acetylate histones; HDACs deacetylate histones; Interaction of NuRD complexes with transcription factors; NuRD complex assembly
DNA Repair: Cleavage of the damaged purine; Cleavage of the damaged pyrimidine; Nonhomologous End-Joining (NHEJ); Processing of DNA double-strand break ends; Recognition and association of DNA glycosylase with site containing an affected purine; Recognition and association of DNA glycosylase with site containing an affected pyrimidine; Recruitment and ATM-mediated phosphorylation of repair and signaling proteins at DNA double strand breaks
Cell Cycle: Condensation of Prophase Chromosomes; Deposition of new CENPA-containing nucleosomes at the centromere; G2/M DNA damage checkpoint; Inhibition of DNA recombination at telomere; Packaging Of Telomere Ends
Developmental Biology: Activation of anterior HOX genes in hindbrain development during early embryogenesis; Chromatin modifications during the maternal to zygotic transition (MZT); Replacement of protamines by nucleosomes in the male pronucleus; Transcriptional regulation of granulopoiesis
Disease: Defective pyroptosis; Dengue Virus-Host Interactions
and 18 more pathways
Gene Ontology:
Molecular function: DNA binding; structural constituent of chromatin; histone binding; protein heterodimerization activity
Biological process: nucleosome assembly; chromatin organization; nucleosome disassembly; sperm DNA condensation
Cellular component: chromosome, telomeric region; nucleosome; nucleus; chromosome; nucleoplasm; cell surface
Genetic constraint (gnomAD): Loss-of-function variants: 5 observed, 5.67 expected, observed/expected ratio (o/e) 0.88, 90% interval 0.46 to 1.71. That is too few expected variants to judge how well the gene tolerates losing a copy. Missense variants: 210 observed, 168.49 expected, observed/expected ratio (o/e) 1.25, 90% interval 1.11 to 1.4. Synonymous variants: 131 observed, 61.13 expected, observed/expected ratio (o/e) 2.14.
Homologues: Orthologues: chimpanzee H2BC1 (100% identical), macaque H2BC1 (98% identical), mouse H2bc1 (94% identical), pig H2BC1 (94% identical), rat H2bc1 (94% identical). Paralogues in human: H2BC13 (86% identical), H2BC15 (86% identical), H2BC21 (86% identical), H2BC26 (86% identical), H2BC3 (86% identical), H2BC10 (85% identical), H2BC11 (85% identical), H2BC17 (85% identical), H2BC4 (85% identical), H2BC5 (85% identical), H2BC6 (85% identical), H2BC7 (85% identical), and 9 more.
Diseases named in the same sentence as H2BC1 in open-access papers:
H2BC1 is named in the same sentence as 11 diseases in open-access papers, as found by Europe PMC text mining. Sharing a sentence is not in itself a finding about the gene and the disease. The quoted sentences say what the papers report.
cholangiocarcinoma (1 paper, 2022). A carcinoma that arises from the intrahepatic biliary tree (intrahepatic cholangiocarcinoma) or from the junction, or adjacent to the junction, of the right and left hepatic ducts (hilar cholangiocarcinoma). "H2BC1 was not expressed in almost all tumor types, while the other H2B genes were differentially expressed in cholangiocarcinoma, esophageal carcinoma, glioblastoma multiforme (GBM), head and neck squamous cell carcinoma, and cutaneous melanoma." (PMID 36387186, 2022).
H2BC1 also shares sentences with these, for which no sentence is quoted: Infertility (5 papers); cancer (1); cutaneous melanoma (1); esophageal carcinoma (1); glioblastoma multiforme (1); head and neck squamous cell carcinoma (1); male infertility (1); sterility (1); tumor (1); varicocele (1).